COL1A2 (collagen type I alpha 2 chain)
Description:
Type I collagen is a member of group I collagen (fibrillar forming collagen).
Synonyms: EDSARTH2; EDSCV; OI4
Tractability: Antibody: its Gene Ontology location is reachable by antibodies, with high confidence; UniProt places it where antibodies can reach, with medium confidence; UniProt predicts a signal peptide or a membrane-spanning region. Other modalities: an approved drug acts on it.
Target class: Structural protein
Gene: Protein-coding gene on chromosome 7 (94,394,820 to 94,431,227, forward strand). Ensembl gene ENSG00000164692.
Subcellular location: Secreted, extracellular space, extracellular matrix
Subcellular location (Human Protein Atlas): Endoplasmic reticulum; Predicted to be secreted
Pathways (Reactome):
Extracellular matrix organization: Anchoring fibril formation; Assembly of collagen fibrils and other multimeric structures; Collagen biosynthesis and modifying enzymes; Collagen chain trimerization; Collagen degradation; Crosslinking of collagen fibrils; ECM proteoglycans; Fibronectin matrix formation; Integrin cell surface interactions; Non-integrin membrane-ECM interactions; Syndecan interactions
Disease: Defective VWF binding to collagen type I; Defective VWF cleavage by ADAMTS13 variant; Defective binding of VWF variant to GPIb:IX:V; Enhanced binding of GP1BA variant to VWF multimer:collagen; Enhanced cleavage of VWF variant by ADAMTS13
Hemostasis: Cell surface interactions at the vascular wall; GP1b-IX-V activation signalling; GPVI-mediated activation cascade; Platelet Adhesion to exposed collagen; Platelet Aggregation (Plug Formation)
Immune System: Immunoregulatory interactions between a Lymphoid and a non-Lymphoid cell; Interleukin-4 and Interleukin-13 signaling
Signal Transduction: MET activates PTK2 signaling; SMAD2/SMAD3:SMAD4 heterotrimer regulates transcription
Developmental Biology: Developmental Lineage of Pancreatic Ductal Cells
Vesicle-mediated transport: Scavenging by Class A Receptors
Gene Ontology:
Molecular function: extracellular matrix structural constituent conferring tensile strength; identical protein binding; platelet-derived growth factor binding; protease binding; protein binding; protein-macromolecule adaptor activity; extracellular matrix structural constituent; SMAD binding
Biological process: blood vessel development; collagen fibril organization; regulation of blood pressure; Rho protein signal transduction; skeletal system development; skin morphogenesis; transforming growth factor beta receptor signaling pathway; odontogenesis; skin development; animal organ development
Cellular component: collagen type I trimer; endoplasmic reticulum; extracellular exosome; extracellular matrix; extracellular region; endoplasmic reticulum lumen; collagen trimer; fibrillar collagen trimer
Genetic constraint (gnomAD): Loss-of-function variants: 43 observed, 163.73 expected, observed/expected ratio (o/e) 0.26, 90% interval 0.2 to 0.34. The upper end of that interval is the gene's LOEUF score, 0.34, which puts it in group 1 of 6, group 1 being the genes least tolerant of losing a copy. Missense variants: 1,404 observed, 1,818.3 expected, observed/expected ratio (o/e) 0.77, 90% interval 0.74 to 0.81. Synonymous variants: 641 observed, 611.26 expected, observed/expected ratio (o/e) 1.05, 90% interval 0.98 to 1.12.
Gene-disease validity (ClinGen):
ClinGen rates the evidence that COL1A2 causes each of these diseases.
COL1A2-related Ehlers-Danlos syndrome (autosomal dominant): Definitive. Any Ehler-Danlos syndrome caused by any variant in the COL1A2 gene.
COL1A2-related osteogenesis imperfecta (autosomal dominant): Definitive. Any osteogenesis imperfecta in which the cause of the disease is a variant in the COL1A2 gene.
Ehlers-Danlos syndrome, cardiac valvular type (autosomal recessive): Definitive. A form of Ehlers-Danlos syndrome characterized by soft skin, skin hyperextensibility, easy bruisability, atrophic scar formation, joint hypermobility and cardiac valvular defects comprising mitral and/or aortic valve insufficiency.
congenital heart disease (inheritance undetermined): Disputed. A heart disease that is present at birth.
Homologues: Orthologues: chimpanzee COL1A2 (99% identical), dog COL1A2 (95% identical), rabbit COL1A2 (94% identical), pig COL1A2 (94% identical), macaque COL1A2 (92% identical), rat Col1a2 (91% identical), mouse Col1a2 (90% identical), guinea pig COL1A2 (82% identical), tropical clawed frog col1a2 (75% identical), zebrafish col1a2 (71% identical). Paralogues in human: COL2A1 (64% identical), COL1A1 (64% identical), COL3A1 (57% identical), COL5A2 (57% identical), COL5A1 (42% identical), COL11A1 (42% identical), COL11A2 (41% identical), COL5A3 (39% identical), COL4A5 (38% identical), COL4A1 (38% identical), COL4A2 (36% identical), COL4A4 (35% identical), and 25 more.
Diseases named in the same sentence as COL1A2 in open-access papers:
COL1A2 is named in the same sentence as 303 diseases in open-access papers, as found by Europe PMC text mining. Sharing a sentence is not in itself a finding about the gene and the disease. The quoted sentences say what the papers report.
osteogenesis imperfecta (212 papers, 2004 to 2026). Osteogenesis imperfecta (OI) comprises a heterogeneous group of genetic disorders characterized by increased bone fragility, low bone mass, and susceptibility to bone fractures with variable severity. "In Europe, approximately 85–90% of individuals with Osteogenesis Imperfecta (OI) have dominant pathogenic variants in the Col1a1 or Col1a2 genes whilst for Asian, especially Indian and Chinese cohorts, this ratio is much lower." (PMID 39908220, 2025). "Variants in COL1A2 are known to cause osteogenesis imperfecta and rare EDS subtypes, including the arthrochalasia and cardiac-valvular types." (PMID 41465473, 2025). "Mutations in COL1A1 and COL1A2 genes can lead to osteogenesis imperfecta and congenital osteoporosis." (PMID 40832109, 2025). "Research indicates that 90% of osteogenesis imperfecta (OI) cases result from pathogenic variants in the COL1A1 or COL1A2 genes, which encode the α1 and α2 chains of type I collagen, respectively." (PMID 40567897, 2025). "In Polish patients with osteogenesis imperfecta (OI), mutations in the COL1A2 gene yielded a variety of phenotypes." (PMID 40563416, 2025). "The COL1A2 gene, classically linked with osteogenesis imperfecta and Ehler-Danlos syndrome (EDS), has been recently associated with hereditary thoracic aortic aneurysm and dissection disease complex (TAAD), suggesting a genetic overlap between SCAD and TAAD." (PMID 39654947, 2024). "Mutations in COL1A1 and COL1A2 have profound implications, leading to osteogenesis imperfecta, a debilitating condition characterized by brittle bones and weakened connective tissues." (PMID 38384607, 2024). "Mutations in the COL1A1 and COL1A2 genes can lead to osteogenesis imperfecta inherited in an autosomal dominant manner." (PMID 38308345, 2024). "Mutations in Col1a2 are associated with osteogenesis imperfecta, while mutations in Col2a1 and Col9a2 are linked to Stickler syndrome." (PMID 38413848, 2024). "Mutations within genes encoding type I collagen, like COL1A1 and COL1A2, can result in conditions such as osteogenesis imperfecta and Ehlers-Danlos syndrome." (PMID 38384607, 2024). "Mutations within the COL1A1 and COL1A2 genes, responsible for encoding type I collagen, can weaken connective tissue, leading to conditions such as osteogenesis imperfecta and Ehlers-Danlos syndrome." (PMID 38384607, 2024). "The most expressed gene, Col1a2, encodes type I collagen, the main component of connective tissue, and mutations in the Col1a2 gene are known to cause osteogenesis imperfecta." (PMID 37545501, 2023). "Most of them cause known monogenic disorders, such as osteogenesis imperfecta (COL1A1/COL1A2), pycnodysostosis (CTSK), X-linked osteoporosis (PLS3), osteopetrosis, X-linked hypophosphatemia (PHEX), and osteoporosis pseudoglioma syndrome (LRP5)." (PMID 37731773, 2023). "Mutations in the COL1A1 and COL1A2 genes, which encode type I collagen, are present in around 85%-90% of osteogenesis imperfecta (OI) patients." (PMID 37457877, 2023). "Correspondingly, the mutation of COL1A2 can cause Osteogenesis Imperfecta (OI), and is close to the central region of the helical chain; the osteoblast differentiation ability is affected." (PMID 37570352, 2023). "Nonetheless, genetic mutations in either the Col1a1 or Col1a2 genes in humans can result in various subtypes of osteogenesis imperfecta syndrome, commonly known as brittle bone disease." (PMID 37895821, 2023). "The most prevalent heritable bone fragility disorder is osteogenesis imperfecta (OI) which is typically linked with autosomal dominant mutations in the COL1A1 or COL1A2 type I collagen alpha chain genes." (PMID 36497201, 2022). "In sheep, frameshift in OBSL1 has been shown to affect brachygnathia inferior, and mutations in COL1A1 and COL1A2 cause osteogenesis imperfecta." (PMID 35008901, 2022).
osteogenesis imperfecta (continued). "Osteogenesis imperfecta (OI) is a disorder of connective tissue generally associated with dominantly inherited pathogenic variants in COL1A1 or COL1A2 genes." (PMID 36077325, 2022). "In the majority of cases, osteogenesis imperfecta is caused by mutations in COL1A1 or COL1A2, which are genes that encode the two collagen type I alpha chains." (PMID 35804365, 2022). "According to the international database on osteogenesis imperfecta, the vast majority of mutations in the COL1A2 gene are missense mutations, which account for approximately 74%." (PMID 35052464, 2022). "Osteogenesis imperfecta is commonly associated with mutations of the genes encoding for type I collagen (COL1A1/COL1A2)." (PMID 34036147, 2021). "Summary of the effects of substitution for glycine in lethal regions of the COL1A1 and COL1A2 gene with the number of mutations resulting in each type of Osteogenesis imperfecta." (PMID 34306033, 2021). "In the early 1980s, mutations in two genes of collagen type I (COL1A1 and COL1A2)were first associated with an autosomal dominant inheritance type of osteogenesis imperfecta." (PMID 33659802, 2020). "Further, homo-trimers due to COL1A2 mutations have been reported in patients and manifested in forms of osteogenesis imperfecta or Ehlers-Danlos syndrome." (PMID 33370286, 2020). "Mice carrying Col1a2 mutations in mouse models of human osteogenesis imperfecta also exhibit decreased bone volume, compact bone thickness, and abnormal compact bone morphology." (PMID 33207791, 2020). "Collagen-DyProQ has immediate applications in studying the synthesis, trafficking, secretion, and degradation of collagen-I caused by mutations in Col1a1 and Col1a2, such as osteogenesis imperfecta, the Ehlers-Danlos syndromes, and Caffey disease." (PMID 32927811, 2020). "Mutation of COL1A2 (fetuses 25 and 26) is thought to be associated with osteogenesis imperfecta, a congenital disease characterized by fragile bones, multiple fractures, blue sclera, dentinogenesis imperfecta, and deafness." (PMID 31566912, 2019). "Osteogenesis imperfecta, a severe genetic disorder manifested by increased bone fragility and low bone mass, is included in the diseases associated with COL1A2." (PMID 31651232, 2019). "Osteogenesis imperfecta is a clinically heterogenous disease caused by defective collagen syntesis associated with a mutation in the COL1A1 or COL1A2 genes." (PMID 28904723, 2017). "COL1A2 gene encodes one of the chains for type I collagen and mutations in this gene produced an osteogenesis imperfecta a type IV phenotype." (PMID 28533732, 2017). "Mutations in COL1A2 or its partner COL1A1 that encode type I collagen can cause dominant inheritance of osteogenesis imperfecta." (PMID 27711115, 2016). "In the current study, we conducted mutational analysis of the COL1A1 and COL1A2 genes among 91 Vietnamese patients with osteogenesis imperfecta." (PMID 27519266, 2016). "Dominant mutations in COL1A1 or COL1A2 cause classical osteogenesis imperfecta (OI), with susceptibility to fractures from minimal trauma and growth deficiency." (PMID 24968150, 2014). "Mutations in COL1A1 and COL1A2 have implicated in the inheritance of osteogenesis imperfecta and have a relationship with bone mineral density in Chinese populations." (PMID 22808055, 2012). "Osteogenesis imperfecta patients from four Old Order Amish families, descended from a single founding couple, have a single Gly610Cys mutation in COL1A2, and yet have variable clinical expressivity of the disease." (PMID 19331686, 2009). "While osteogenesis imperfecta and osteoporosis are distinct conditions, rare deleterious variants in COL1A2 are associated with reduced BMD and increased fracture risk in population-based studies, suggesting a potential overlap in genetic pathways contributing to bone strength and fragility." (PMID 40411668, 2025).
osteogenesis imperfecta (continued). "Notably, mutations in the COL1A1 and COL1A2 genes, responsible for encoding type I collagen, have been linked to the weakening of connective tissues and the onset of conditions such as osteogenesis imperfecta and Ehlers-Danlos syndrome." (PMID 38384607, 2024). "Notably, mutations in the COL1A1 and COL1A2 genes, responsible for encoding type I collagen, are linked to rare genetic disorders like osteogenesis imperfecta and specific types of Ehlers-Danlos syndrome." (PMID 38384607, 2024). "Interestingly, another de novo mutation event in the COL1A2 gene caused a severe form of osteogenesis imperfecta in a brother of the PKD-affected index female." (PMID 37372390, 2023). "Genetic analysis revealed osteogenesis imperfecta (gene mutation COL1A2)." (PMID 37114012, 2023). "We believe that the best genetic testing approach would be to obtain whole-exome sequencing (WES) of the proband′s genomic DNA, which would accurately identify pathological sequence variations in COL1A1 and COL1A2 that cause osteogenesis imperfecta (OI) and in the many genes causing AI." (PMID 35627243, 2022). "Supporting our hypothesis, osteogenesis imperfecta caused by mutations in type 1 collagen genes (COL1A1/COL1A2) is associated with communicating hydrocephalus." (PMID 34425881, 2021). "Although the majority of heterozygous mutations in COL1A1 or COL1A2, encoding the pro-α1- and pro-α2-chain of type I collagen, respectively, result in the brittle bone disorder osteogenesis imperfecta (OI), specific type I collagen defects can also give rise to rare EDS subtypes." (PMID 34712265, 2021). "Supporting our hypothesis, osteogenesis imperfecta caused by mutations in type I collagen genes (COL1A1/COL1A2) is associated with hemorrhagic diathesis, and is also hypothesized to be associated with vascular fragility." (PMID 34200258, 2021). "Genetic mutations in Col1a1 or Col1a2 genes (or other genes affecting Col1 biosynthesis) in humans lead to multiple subtypes of Osteogenesis Imperfecta (OI) syndrome, a bone disease referred to as the ‘brittle bone disease’3–5." (PMID 34893625, 2021). "The mutation of COL1A1 and COL1A2 in MSCs could cause osteogenesis imperfecta, it likely that COL1A1 and COL1A2 play an important role in osteogenesis differentiation from MSCs." (PMID 32489333, 2020). "Indeed, mutations in collagen type I (COL1A1 and COL1A2) are responsible for mild to severe osteogenesis imperfecta that can be revealed in adulthood." (PMID 30283887, 2018). "Such a possibility is consistent with another report where a osteogenesis imperfecta COL1A2 G610C mutation causes procollagen I misfolding in the ER of osteoblasts and abnormal osteoblast differentiation, but did not induce the classical UPR mediators BiP or Xbp1-spliced form." (PMID 30024379, 2018). "However, the only reported mouse model for OI with a Col1a2 mutation is osteogenesis imperfecta-murine (oim)." (PMID 19594296, 2010). "Prenatal cell free DNA testing (Vistara) identified a COL1A2 gene mutation, consistent with Osteogenesis Imperfecta (OI) Type II." (PMID 40567522, 2025). "Osteogenesis Imperfecta (OI) is a genetic disorder caused by mutations in the COL1A1 or COL1A2 genes, leading to alterations in type I collagen." (PMID 40245284, 2025). "In comparison to other published accounts of neonatal osteogenesis imperfecta (OI), our work delivers distinctive perspectives on the management of an infant with a confirmed COL1A2 mutation." (PMID 41480373, 2025). "Variants in COL1A1 and COL1A2, especially glycine-related missense variants, are classically associated with osteogenesis imperfecta (OI), a heritable disorder characterized by bone fractures, hearing loss, and dental impairments." (PMID 38892036, 2024). "COL1A1 or COL1A2 mutations are the major cause of osteogenesis imperfecta (OI) with variable aortic and mitral valve disease and features of EDS." (PMID 38370698, 2024).